IL4 (interleukin 4)
Diseases named in the same sentence as IL4 in open-access papers (continued):
Sharing a sentence is not in itself a finding about the gene and the disease.
tumor (continued). "Human monocytes expressing FcεRI on the cell surface triggered IgE-mediated ADCC of tumour cells, while IL-4 stimulated monocytes killed FRα-expressing tumour cells by both ADCC and ADCP, compared to background levels of tumour cell death with NIP IgE and no IgE controls." (PMID 31544825, 2019). "But, there is still some evidence that IL‐4 is a tumor‐promoting molecule." (PMID 30729744, 2019). "When we further analyzed the tumor tissue for pro- and anti-inflammatory markers, we observed a trend towards more inflammation, together with lower expression of markers typical for M(IL4+IL13)-polarized macrophages." (PMID 31178956, 2019). "Secretion of IL-4 is induced when tumor cells are cocultured with CD11b+ cells." (PMID 31798581, 2019). "It is suggested that tobacco can decrease the transcription rate of IL-4 gene as this may have anti-tumor effects." (PMID 31582940, 2019). "TNF-α and IFN-у appear to enhance eosinophilic production of pro-inflammatory Th1-type chemokines such as CXCL9 and CXCL10 whereas TNF-α and IL-4 stimulate eosinophilic production of Th2-type chemokines, which sustain a more immunosuppressive tumor microenvironment." (PMID 31730503, 2019). "Th1 cells are pro-inflammatory and express IFN-γ to promote APCs and prime CD8+ cells, while Th2 cells may encourage tumor growth through IL-5 production, although they do recruit eosinophils through IL-4 and IL-13." (PMID 30931508, 2019). "IL-4 promotes polarization into the M2-Mφ phenotype and promotes tumor progression." (PMID 31798581, 2019). "Therefore, a recipe consisting of IL-4, IL-10, M-CSF, and tumor-conditioned media was utilized in this study to generate monocyte-derived TAM in vitro." (PMID 31138333, 2019). "These two helper T cell subtypes were co-enriched in the same patient clusters, despite being thought to be associated with different processes; that is, Th1 cells induce IFNG expression and anti-tumor effects while Th2 release IL-4 and IL-10, which help allow for tumor-escape." (PMID 30956762, 2019). "Plasma IL-4, IL-6 and TNFα levels were significantly increased in tumor-bearing versus normal mice." (PMID 31752313, 2019). "Afterwards, the expression levels of 12 cytokines including IL-1a, IL-1b, IL-2, IL-4, IL-6, IL-8, IL-10, IL-12, IL-17A, TNFα, IFNγ and GM-CSF in secretome of hWJ-MSCs alone as well as in supernatant of tumor cells before and after treatment with hWJ-MSCs secretome were evaluated." (PMID 31857970, 2019). "Furthermore, the BTK/ITK inhibitor ibrutinib efficiently limits the IL-4-producing Th2 cell population and inhibits cytokine production and direct signaling to induce the activation of tumor cells." (PMID 30814910, 2019). "Finally, a study of intracavitary administration of pan-ErbB/IL-4 CAR T cells targeting patient derived MPM xenografts in SCID mice showed tumor regression or cure in all mice." (PMID 30804938, 2019). "Thus, our data suggests that in the IL-4+ tumor milieu, 4/21 ICR-CAR T cells can maintain an activated but less exhausted status and persistently eliminate tumor cells." (PMID 31379876, 2019). "Optimal activation of tumour-antigen-specific T cells overexpressing IL-4R–IL-7R CSRs occurred only when engineered T cells encountered their specific tumour antigen and elevated IL-4 was present in the tumour microenvironment." (PMID 30413825, 2019). "We found that reduced IL-4 secretion is mainly attributed to STAT6 deficiency in CD11b+ cells but not tumor cells." (PMID 31798581, 2019). "M1 macrophages act in microbiocidal and anti-tumor activity with the secretion of IL1β, IL12 and TNF-α, whereas M2 macrophages act in tissue remodeling, immune tolerance and tumor progression with the secretion of IL4, IL10 and transforming growth factor (TGF)-β." (PMID 31408948, 2019). "The mechanism that amphotericin B disrupts the balance of the tumor microenvironment may be involved in the IL-4/IL-13-STAT6 B7-H1 signaling pathway." (PMID 29695237, 2018).
tumor (continued). "Also, the level of inflammatory markers including TNFα, NF-κB p50 subunit and IL-4 in tumor tissues showed positive correlation with the level of ALCAM transcripts." (PMID 29315254, 2018). "Furthermore, in a spontaneous mouse model of mammary tumorigenesis, intratumoral CD4+ T cells produced cytokines, such as IL-4 and IL-13, which favor the activation and polarization of tumor-promoting immune cells, such as TAMs." (PMID 30355585, 2018). "EGFR correlation with IL-4 signaling axis genes and correlation between IL-4 tumor and normal." (PMID 29621254, 2018). "Splenic IL-8 was associated with weight and muscle loss and had a negative association with the same tumor proteins associated with increased TFBW (IL-4, Flt-3L, IFNγ, IL-7) and skeletal muscle weights (Flt-3L, IFNγ)." (PMID 30513792, 2018). "It is known that the anti-inflammatory cytokines IL-10 and IL-4 are involved in the maintenance of Th2 response profile that, with consequent suppression of the Th1 response, produces a microenvironment favorable to tumor growth." (PMID 30200386, 2018). "As CCR3 is also expressed on eosinophils and subpopulations of Th2 cells, CCR3+ cells secreting CCL11 and IL-4 may produce a Th2-dominant microenvironment, which is suitable for tumor growth." (PMID 29915722, 2018). "Additionally, the immune suppressive factor TGFβ, but not IL-10, inhibited CD11b surface expression; TGFβ, IL-4 and tumor cell conditioned medium (TCM) each also suppressed Cd11b mRNA expression." (PMID 30568188, 2018). "Instead of injecting a peptide that is presented to an APC, autologous dendritic cells sourced from peripheral blood monocytes are primed with tumour lysate from the patients’ own tumour in the presence of growth factors such as interleukin-4 and granulocyte macrophage colony stimulating factor." (PMID 29854316, 2018). "Salmonella induced upregulation of Il2, Il4, Ifng, and Tnfa gene expression in the tumor, which might be involved in the intratumoral recruitment of CD4+ T, CD8+ T, and NK cells." (PMID 29410666, 2018). "Subsequently, the recruited monocytes transform into TAMs stimulated by cell factors (like macrophage colony-stimulating factor (M-CSF), vascular permeability factor (VEGF)-1, IL-4, IL-10, IL-13), and then, tumor angiogenesis is induced by TAM-secreted angiogenesis factors." (PMID 29458367, 2018). "Furthermore, mice vaccinated with AntpMAPMUC1tet + CpG show enhanced antigen specific IFN-γ and IL-4 T cell responses compared with AntpMAPMUC1tet vaccination alone and induced delayed tumour growth." (PMID 30200528, 2018). "Similarly, the expansion of 1G.4/7ICR T cells was superior to their 1G counterparts when we cultured both in the presence of recombinant IL4 with weekly antigen stimulation from irradiated MDA MB 468 tumor cells." (PMID 29747685, 2018). "Studies have shown that IL-4 can lead to regulation of anti-tumor immune responses." (PMID 30127820, 2018). "IL-4 supports cellular proliferation of human tumor cell lines in a concentration-dependent manner." (PMID 30042722, 2018). "It has also been observed that IL-4 secreting CD4+ T lymphocytes were able to indirectly promote tumor invasiveness and pulmonary metastasis of mammary tumors via enhancing pro-tumor properties of tumor associated macrophages." (PMID 30356678, 2018). "Th2 polarization and IL-4 have been shown to promote tumor growth and metastasis." (PMID 29403003, 2018). "The data obtained in the present study suggest a certain toxic effect of the TiO2 coating that is mediated by inhibition of the genetic (preserving the length of telomeric DNA sequences) and secretory (IL-4) mechanisms supporting the proliferation of tumor Jurkat T cells." (PMID 29495627, 2018). "In addition, a previous study showed that carnosol has anti-tumor capacity through prevention of Treg cell differentiation, decreasing IL-4 and IL-10 production, and enhancing IFN-γ secretion in tumor-associated lymphocyte populations." (PMID 30150982, 2018).
tumor (continued). "Moreover, co-immunisation with the adjuvant CpG promotes enhanced antigen specific IFN-γ and IL-4 T cell responses, induces a Th1 response, characterised by a higher ratio of IgG2a /IgG1 antibodies and delays tumour growth in vivo." (PMID 30200528, 2018). "IGF‐1 mRNA expression was more potently induced by IL‐4 than by LPS, in agreement with its proposed role as marker for wound‐healing macrophages, which contribute to tumor progression." (PMID 29907597, 2018). "Also, the use of Salmonella enterica in the bactofection of plasmids encoding interleukin-4 or interleukin-18 induced a systemic increase in IFN-γ and was efficient in delaying tumor growth and prolonging survival in a melanoma murine model." (PMID 30302344, 2018). "We next explored whether co-expression of the 4/7ICR and the 1G CAR produced superior anti-tumor effects in a long-term tumor model that recapitulated an IL4-rich milieu." (PMID 29747685, 2018). "While co-expressing the 4/7ICR with the CAR improved expansion and anti-tumor activity of T cells in the presence of IL4, this receptor complementation approach of tumor targeting does not address the risk of immune escape due to mutation or loss of the target molecules." (PMID 29747685, 2018). "In addition, neutralization of ST2Lsignificantly decreased Treg cells and ST2L+Treg both in spleen and in tumortissue of tumor-bearing mice (Figure 5Eand F) and inhibited the protein levels of IL-4, IL-10, and IL-13." (PMID 29950152, 2018). "However, given the role of MUC1 and IL4 in tumor progression and metastasis, it is highly unlikely that the tumor will downregulate either one or both of these molecules." (PMID 29747685, 2018). "In conclusion, IL‐4 increases a PC3 subpopulation with tumor‐initiating characteristics." (PMID 29236307, 2018). "These positive feedback loops are generated by cytokines such as TGF-β, Interleukin-10 and Interleukin-4, which are responsible for the polarization of monocytes and M1 macrophages into pro-tumor M2 macrophages, and the polarization of naive helper T cells intopro-tumor Th2 cells." (PMID 35847834, 2018). "To characterize the human macrophages in HSC-NOG-hIL-6 Tg mice further, we examined the expression of IL-4Rα in human macrophages, as IL-4 is one of the factors supporting the differentiation of TAMs and expression of the IL-4 receptor is a marker for delineating TAMs in tumor." (PMID 29456539, 2018). "To characterize the mutation status and gene expression levels of the cytokines IL-4 and IL-13, their receptors IL-4Rα, IL-13Rα1/2, and the oncogenes c-Met and EGFR, we performed exome and RNA-seq analysis on DIPG tissues (38 tumor exome, 26 normal exome, 28 tumor RNA, 18 normal RNA)." (PMID 29621254, 2018). "The differences can be explained by the different mechanisms suggesting that different mechanisms of tumor development and the role of IL-4 genes in different tumors may be different." (PMID 29137245, 2017). "The result differs from the study using MMTV-PyMT mice on the C57/BL6 background, in which most tumor macrophages were characterized as CD206- tumor associated macrophages and were not affected by IL-4 deficiency." (PMID 27909985, 2017). "Therefore, we further analyzed the percentages of IL-17A-, IL-6-, IFN-γ-, IL-4-, granulocyte macrophage colony stimulating factor (GM-CSF)- and IL-1β-producing cells in tumor-infiltrating cell populations from mice administered L-4F or Sc-4F." (PMID 29245934, 2017). "As IL-4 can also promote tumorigenesis through alteration of the tumor suppressing activity of monocytes and macrophages, the overlapping phenotypical and functional characteristics of TFH and TH2 cells might also favor the tumor niche in FL." (PMID 29340116, 2017). "The autocrine origin of IL-4 is now believed to be an indicator of tumor aggressiveness." (PMID 28927416, 2017).
tumor (continued). "Interestingly, given that IL-4 receptors (IL-4R) are highly expressed in OC and other neoplasia, the IL-4/IL-4R pair has been attempted as a target for OC immunotherapy." (PMID 28966800, 2017). "Early studies suggested that IL-4 could help other cytokines or drugs to remove and suppress growth of tumor cells." (PMID 29137245, 2017). "This strongly supports the hypothesis that IL-4/STAT6 signaling may be beneficial to tumor growth possibly by several mechanisms, including gaining resistance to apoptosis and escaping the immune surveillance." (PMID 28927416, 2017). "Moreover, TAM phenotype expresses Arg1 and TGF-β in order to recruit Th2 lymphocytes to the tumor site leading to an increase in IL-4 production and maintenance of the M2 population." (PMID 28970834, 2017). "However, our results differ, at least in part, from a previous report that examined the effect of IL-4 on reactive oxygen production by human tumor cells." (PMID 28498822, 2017). "However, M2-type macrophages, stimulated by interleukin-4 (IL-4) or IL-13, have the ability to promote tumor growth and progression." (PMID 29348856, 2017). "In this strategy, the blockade could be achieved either by inhibiting IL-4R or by neutralizing the IL-4 present in the tumor environment." (PMID 28927416, 2017). "This tumor-mediated modulation of immunity is demonstrated by an overall decrease of CD4+ T-cells coupled with a shift to a T helper-2 phenotype (increased expression of IL-4 and reduced expression of IL-2) in HNSCC patients." (PMID 28977830, 2017). "In addition to cell proliferation and survival, IL-4/IL-4R signal plays a key role in tumor metastasis." (PMID 28927416, 2017). "This adaptation to the IL-4-producing tumour microenvironment may play a critical role in the promotion of novel tumour-initiating foci, and possibly tumour initiation at distant sites." (PMID 28553931, 2017). "It has been suggested that interleukin-4 and -5 produced from tumor-infiltrating T cells in tumors, might promote tumor growth and spreading." (PMID 29340113, 2017). "Therefore, it is possible that in a tumor microenvironment IL4 will render cancer cells more resistant to CHOP treatment." (PMID 28445949, 2017). "For instance, the chemokine CCL2 and macrophage colony-stimulating factor were shown to recruit inflammatory monocytes to the tumour site, and then differentiate into TAMs in response to IL-4, IL-10, IL-13 and other cytokines in the tumour microenvironment and promote tumour metastasis." (PMID 29065107, 2017). "Recently, a growing body of literature claimed that cytokines are not only produced by the immune cells present in the tumor microenvironment, the autocrine origin of some inflammatory cytokines, especially IL-1, IL-4 and IL-6, was observed in large range of solid tumors." (PMID 28927416, 2017). "Collectively, our data suggest that the presence of IL4 in the tumor microenvironment of EBV+ DLBCL may alter the outcome of CHOP treatment towards a poor prognosis." (PMID 28445949, 2017). "In addition to increasing NOX1-dependent cell cycle progression, as reported in this study, IL-4 has been demonstrated to stimulate tumor cell proliferation by enhancing the expression of anti-apoptotic proteins and/or signaling through the MAPK pathway." (PMID 28498822, 2017). "Both molecules contribute to carcinogenesis by stimulating cancer cell proliferation, inhibiting apoptosis, increasing invasiveness, and modulating inflammation and immunity through the induced release of Th2 cytokines, such as IL-10, TGF-β, IL-4, and IL-13, by TAMs and the tumor cells." (PMID 28970834, 2017). "This cytokine acts concurrently with IL-3 and IL-4 to stimulate the proliferation of mast cells, peripheral blood lymphocytes, and macrophages, and their anti-inflammatory action has been suggested in tumor microenvironment." (PMID 26989335, 2016).
tumor (continued). "Tumor-associated macrophages (TAMs) may represent up to 50% of the tumor mass, and most TAMs have the M2 phenotype due to the signals in the tumor microenvironment, such as IL-4 and TGF-β." (PMID 27975071, 2016). "Our findings represent a conceptual advance in the understanding of IR-induced changes in the tumor microenvironment, and suggest that a gene therapy that inhibits IL-4 combined with radiotherapy is a promising strategy for preventing aggressive tumor behavior." (PMID 27895317, 2016). "Finally, IR-induced IL-4 promotes tumor progression and metastasis by increasing β-catenin/Stat6 through activation of JAK/JNK in human cancer cells." (PMID 27895317, 2016). "In addition, Th2 immune responses have been shown to induce IL-4- and eosinophil-dependent anti-tumor activity." (PMID 27148488, 2016). "IL-4 was significantly reduced in the tumour microenvironment following NAC." (PMID 27777963, 2016). "Furthermore, we looked at gene expression of IL-4 and IL-13, which typically promote alternative activation of macrophages into M2 cells, which is generally tumor promoting." (PMID 27827906, 2016). "The M1 population is thought to be beneficial in a tumor environment (including solid tumors and circulating tumor cells) but this environment is overwhelmed by anti-inflammatory signals, and type-II cytokines (e.g. IL-4, IL-10 and IL-13) tend to dominate." (PMID 27564103, 2016). "Thus, despite significant differences to in vivo DCs, GM-CSF and IL-4-derived cDCs remain the most widely used in vitro generated DC type that is used in immunological studies and for tumour immunotherapy." (PMID 27431276, 2016). "However, following stimulation with α-c-myc tag monoclonal antibody or the tumor cells 24JKERB, we detected a range of cytokines, including IL-4, IL-2, IL-17A, TNF-α, IL-6 and IFN-γ from CAR T cells, while no significant response was observed from WT T cells." (PMID 27153556, 2016). "By using adjuvant combination for a DNA vaccine, we found that the levels of lymphocyte proliferation, CTL activity, IFN- γ, IL-4 and IL-12 responses, and tumor protection against TC-1 cells were significantly increased compared to the DNA vaccine with individual adjuvants." (PMID 26811064, 2016). "Because production of IL-4 and IL-13 was markedly upregulated in sST2 low-expressing tumours, we assumed that the proportion of the M2a subset was increased in these tumours." (PMID 27882929, 2016). "IL-4 induces “alternative” activation of M2-like macrophages; and in response to other cytokines, including TGFβ, IL-10, and CSF-1, this macrophage type has been reported to acquire properties that enhance tumor cell growth, invasion and metastasis." (PMID 27563494, 2015). "However, the proportions of CD4, CD8, and CD56 cells are not significantly (P > 0.05) correlated with other clinicopathological parameters, including tumor type, IL-4, and toxicity." (PMID 26515587, 2015). "Third, by RT-qPCR analyses, TANs showed downregulation of anti-tumor genes (e.g., il4, il6, il8, il10, il12, and tnfa) and upregulation of pro-tumor genes such as il1b, which also promotes early cancer angiogenesis, indicating a potential role of TANs in pro-angiogenesis in HCC initiation." (PMID 25828472, 2015). "Type 2 cytokines, including IL-4 and IL-10, downregulate the tumor-specific immune response by directly suppressing the production of Th1 cytokines, which prevents CTL and NK cell activation and by inhibiting tumor antigen presentation by antigen-presenting cells." (PMID 25352158, 2015). "In the 1990s, IL-4 was identified as a potent anti-tumour factor." (PMID 25651850, 2015). "IHC staining of sections from tumor-bearing glands revealed similar levels of CD11b+ cells in both cohorts, indicating that IL-4 did not cause a significant increase in the number of tumor associated myeloid cells (P=0.1449)." (PMID 27563494, 2015).